SUSD1 (sushi domain containing 1)
Synonyms: DKFZP761E1824
Tractability: Antibody: UniProt predicts a signal peptide or a membrane-spanning region. PROTAC: ubiquitination databases record sites on it.
Gene: Protein-coding gene on chromosome 9 (112,040,777 to 112,175,486, reverse strand). Ensembl gene ENSG00000106868.
Subcellular location: Membrane
Subcellular location (Human Protein Atlas): Nucleoplasm
Gene Ontology:
Molecular function: calcium ion binding
Cellular component: membrane
Genetic constraint (gnomAD): Loss-of-function variants: 49 observed, 66.6 expected, observed/expected ratio (o/e) 0.74, 90% interval 0.58 to 0.93. The upper end of that interval is the gene's LOEUF score, 0.93, which puts it in group 3 of 6, group 1 being the genes least tolerant of losing a copy. Missense variants: 697 observed, 784.3 expected, observed/expected ratio (o/e) 0.89, 90% interval 0.83 to 0.95. Synonymous variants: 300 observed, 301.16 expected, observed/expected ratio (o/e) 1, 90% interval 0.91 to 1.1.
Homologues: Orthologues: chimpanzee SUSD1 (96% identical), macaque SUSD1 (91% identical), dog SUSD1 (84% identical), pig SUSD1 (81% identical), guinea pig SUSD1 (79% identical), rabbit SUSD1 (77% identical), mouse Susd1 (74% identical), rat Susd1 (69% identical), tropical clawed frog susd1 (39% identical), zebrafish susd1 (30% identical).
Diseases named in the same sentence as SUSD1 in open-access papers:
SUSD1 is named in the same sentence as 5 diseases in open-access papers, as found by Europe PMC text mining. Sharing a sentence is not in itself a finding about the gene and the disease. The quoted sentences say what the papers report.
Myalgia (1 paper, 2021). "From the whole genome sequencing results, potentially functional SNPs in RHOBTB1 and SUSD1 were found to be highly associated with atorvastatin-induced myalgia." (PMID 33967749, 2021).
venous thromboembolism (1 paper, 2021). Occlusion of the lumen of a vein by a thrombus that has migrated from a distal site via the blood stream. "SNPs in SUSD1 has been previously associated with venous thromboembolism and neurocognitive disabilities." (PMID 33967749, 2021).
SUSD1 also shares sentences with these, for which no sentence is quoted: major depression (1 paper); neurodevelopmental disorder (1); schizophrenia (1).